IL6 (interleukin 6)
Diseases named in the same sentence as IL6 in open-access papers (continued):
Sharing a sentence is not in itself a finding about the gene and the disease.
hypoadiponectinemia (14 papers, 2013 to 2023). "In particular, the hypoadiponectinemia status was previously significantly correlated with increased inflammation, as asessed by IL-6." (PMID 34991564, 2022). "Visceral obesity results in hypoadiponectinemia and an increase in tumor necrosis factor-α, interleukin (IL)-6, and other adipokines, which in turn result in insulin resistance." (PMID 28887474, 2017). "HFD mice also exhibited hypoadiponectinemia and increased serum levels of interleukin-6 (IL-6) and tumor necrosis factor (TNF)-α compared with ND mice." (PMID 26518260, 2015). "Experimental studies proved that adiponectin expression is negatively regulated by pro-inflammatory cytokines, including IL-6 and TNF-α, whereas adiponectin modulates the action and production of TNF-α in various tissues, while hypoadiponectinemia is associated with increased IL-6 levels." (PMID 33738273, 2020). "It depends on both IL-6 and TNF-a, with high serum concentrations related to hypoadiponectinemia and, consequently, to a low anti-inflammatory response." (PMID 37585909, 2023). "Also, hypoadiponectinemia related to systemic inflammation may have a role in the development of NAFLD because adiponectin has anti-inflammatory effects via inhibition of tumor necrosis factor (TNF)-α and IL-6." (PMID 30673698, 2019).
hypogonadism (14 papers, 2012 to 2023). A disorder characterized by decreased function of the gonads. "In brief, in an animal model of hypogonadism, reduced testosterone levels were associated to elevated inflammatory cytokines such as IL-6, IL-1β, and TNF-α." (PMID 37298172, 2023). "An inflammatory pattern, characterized by increased IL-6, was associated with hypogonadism and adiposity." (PMID 35135482, 2022). "High IL-6 levels were associated with hypogonadism at baseline (OR 2.83, 95%CI 1.25–6.43) and the association was stronger for high IL-6 combined with low IL-10 levels (OR 3.10, 95%CI 1.37–7.01)." (PMID 35135482, 2022). "High levels of IL-6 were associated with hypogonadism (OR 2.83, 95%CI 1.25–6.43, p = 0.013)." (PMID 35135482, 2022). "High IL-6 levels were associated with hypogonadism and cardio-metabolic risk factors." (PMID 35135482, 2022). "Briefly, in an animal model of hypogonadism, where there are reduced testosterone levels, inflammatory cytokines such as IL-6, IL-1β, and TNF-α were said to be elevated and only IL-6 was reduced after testosterone treatment." (PMID 36287907, 2022). "One common observation in these studies is that higher levels of IL-6, IL-1β, TNF-α, and CRP were noted in men with testosterone deficiency (hypogonadism)." (PMID 30558178, 2018). "To explore the direct effects of IL-6 on the development hypogonadism in the ApcMin/+ mouse we over-expressed circulating IL-6 for two weeks in weight stable ApcMin/+ mice." (PMID 24285707, 2013). "The purpose of this study was to assess the utility of the ApcMin/+ mouse for the examination of hypogonadism during cancer cachexia and to investigate if IL-6 has a role in this process." (PMID 24285707, 2013). "Our results point to a regulation of hypogonadism by IL-6, as IL-6 signaling inhibition after the initiation of weight loss attenuated the decrease in circulating testosterone and testes mass when compared to PBS treated mice." (PMID 24285707, 2013). "Among CCS, hypogonadism, lower lean body mass, higher daily television/computer screen time, lower physical activity, and higher inflammatory marker IL-6, increased the odds of having a BMD Z-score ≤ -1." (PMID 22455440, 2012). "However, combining a high IL-6 and a low IL-10 yielded an unadjusted OR of 3.10 (95%CI 1.37–7.01, p = 0.007) for hypogonadism." (PMID 35135482, 2022). "We found that male castration increased the recruitment of inflammatory cells and upregulated the expression of TNF-α and IL-6, similar to clinical reports that higher levels of IL-6, IL-1β, and TNF-α were noted in men with testosterone deficiency (hypogonadism)." (PMID 33475136, 2021). "Within the CCS group, the results show that lower lean body mass, lower levels of physical activity, higher daily television viewing time, higher IL-6 levels, hypogonadism and exposure to radiation or steroids increased the likelihood of having a BMD Z-score ≤ -1." (PMID 22455440, 2012). "However, a significant increase in serum IL-6 (p = 0.019) and TGF-β1 (p = 0.025) levels in patients with acromegaly was observed and all patients had concurrent hypogonadism." (PMID 33154456, 2020). "Interestingly, in rodents and primates with hypogonadism, the hyperreactivity of the HPA axis due to stress and increased cytokines such as IL-6 was attenuated by sex hormone replacement." (PMID 28740334, 2017). "Although we can not definitely conclude whether IL-6 acts directly or indirectly in the development of hypogonadism, it appear IL-6 is necessary but not sufficient to induced the hypogonadal condition in the ApcMin/+mouse." (PMID 24285707, 2013).
Large vessel vasculitis (14 papers, 2012 to 2024). A type of vasculitis (inflammation of blood vessel walls) affecting large arteries such as the aorta and branches of the aorta. "Interleukin-6 (IL-6), one of the main proteins implicated in the acute phase reaction, has been recognized as one of the main therapeutic targets in GCA and large vessel vasculitis in general." (PMID 39459361, 2024). "In spite of the success of blocking IL-6 in large vessel vasculitis, relapse rates remain high, suggesting that further study is needed." (PMID 34209028, 2021). "IL-1β, IL-6 and TNF-α produced by macrophages amplify the inflammatory response and lead to the large vessel vasculitis which including fever, weakness, anorexia, weight loss and acute phase response." (PMID 34429489, 2021). "A considerable amount of literature indicates the importance of interleukin-6 (IL-6) in the pathogenesis of large vessel vasculitis." (PMID 31780858, 2019). "Although the mechanism underlying G-CSF-induced large-vessel vasculitis has not been fully clarified, it has been suggested to involve induction of immune mediators such as interleukin (IL)-2 and IL-6, leading to generation of pathological Th17 cells." (PMID 35960391, 2022). "Furthermore, inhibition of IL-6 has been shown to be an effective therapeutic strategy for the management of large vessel vasculitis." (PMID 31780858, 2019). "Examples of these are rituximab in ANCA-associated vasculitis; mepolizumab in eosinophilic granulomatosis with polyangiitis; complement 5a inhibition in ANCA vasculitis; and potentially Interleukin-6 (IL-6) inhibition with tocilizumab in large vessel vasculitis." (PMID 25352843, 2014). "IL-6 inhibitory therapy is applied worldwide as treatment for RA and JIA and is now being used for the treatment of large vessel vasculitis." (PMID 30423923, 2018).
monocytic leukemia (14 papers, 2014 to 2024). "IL-6 secretion by human monocytes and human monocytic leukemia cell line cells are stimulated by HMW adiponectin and does not inhibit LPS-induced IL-6 secretion." (PMID 36131342, 2022). "The Sasa albomarginata extract inhibited inflammatory mediators such as LPS-induced NO, IL-6, and ROS production in mouse monocyte leukemia RAW264.7 cells." (PMID 36330350, 2022). "VPA inhibits nuclear factor κ-B (NFκ-B), TNF-α, and interleukin-6 (IL-6) production in human monocytic leukaemia cells stimulated with lipopolysaccharide." (PMID 27195290, 2016). "Moreover, it inhibited LPS-induced IL-6 expression and production in human monocyte leukemia THP-1 cells differentiated into macrophages." (PMID 36330350, 2022). "To examine whether the engineered bacteria can remove macrophage-derived IL-6 from their environment, we established a model of macrophages by exposing human monocytic leukemia THP-1 cells and human histiocytic lymphoma U-937 cells to PMA for 48 h." (PMID 35155394, 2022). "Hence, to assess the observable effects of miR-338-5p on IL-6 mRNA, we stimulated human monocytic leukemia (THP-1) cells with bacterial lipopolysaccharide (LPS)." (PMID 30871575, 2019). "Similarly, other S100A8 and S100A9 regulators, such as IL-6 and TNFα, have been identified on human monocytic leukemia cells." (PMID 24956170, 2014). "LPS treatment upregulated LINC01270 in the human monocytic leukemia cell line THP-1, and its suppression via siRNA enhanced NF-κB activity and the production of pro-inflammatory cytokines IL-6, IL-8, and MCP-1." (PMID 39682774, 2024). "However, there are several experimental reports that sST2 may have its own anti-inflammatory effects, e.g., direct effects on macrophages via the downregulation of Toll-like receptors, and the inhibition of LPS-induced IL-6 production in a human monocytic leukemia cell line." (PMID 38672063, 2024). "DHA inhibits the inflammatory cytokines, such as IL-6, and TNF-α and IL-1β expression induced by LPS in THP-1 cells, which is the human monocytic leukemia cell line." (PMID 36741381, 2022). "In particular, menadione inhibited nuclear factor kappa-light-chain-enhancer of activated B cell (NF-κB) activation and thereby reduced expression of the proinflammatory cytokines such as IL-1β, IL-6, IL-8, and TNF-α in AGS as well as in THP-1 (monocytic leukemia cell) cell lines." (PMID 30866458, 2019). "Thus, HMW adiponectin increases IL-6 secretion in human monocytes and human monocytic leukemia cell lines but does not suppress lipopolysaccharide (LPS)-induced IL-6 secretion." (PMID 32354030, 2020). "Thus, IL-6 is known to be a potent inducer of cellular synthesis of SAA during inflammation by various cell types including those of the liver such as hepatocytes, Kupffer cells and in human monocytic leukaemia cell lines (THP-1)." (PMID 30597899, 2018).
myeloid leukemia (14 papers, 2008 to 2025). A clonal proliferation of myeloid cells and their precursors in the bone marrow, peripheral blood, and spleen. "Leukemia inhibitory factor (LIF), a member of the interleukin-6 (IL-6) cytokine family, was first recognized for inducing differentiation in myeloid leukemia cells." (PMID 39857986, 2025). "The results showed that in the myeloid leukemia patients, serum levels of IL-6 were different from those of the controls." (PMID 38024543, 2023). "Here we show that PTP1B overexpression is able to inhibit JAK/STAT signalling by IL6 in the M1 myeloid leukemia cell-line, adding another potential target to the list of cytokines regulated by this phosphatase in vivo." (PMID 37316570, 2023). "LIF belongs to the IL-6 cytokine family, and is described as a glycoprotein that inhibits M1 myeloid leukemia cell proliferation and induces differentiation." (PMID 36226317, 2022). "Further, rFIP-mco can significantly reduce the expression levels of TNF-α, IL-1β, and IL-6 in the THP1 cells (human myeloid leukemia mononuclear cells)." (PMID 33193329, 2020). "Initially, GADD45β encoded by MyD118 was identified as a myeloid differentiation primary response gene activated by IL-6 in murine myeloid leukemia cells upon induction of terminal differentiation." (PMID 20942912, 2010). "Experiments using IL-6 stimulation of myeloid leukemia cell lines have shown that IL-6 induces development of mature macrophages." (PMID 19936194, 2008). "Likewise in a similar study in 2010, the serum levels of IL-6 were evaluated in 30 myeloid leukemia patients versus controls." (PMID 38024543, 2023). "Reasons for the limited responses may be due to the presence of myeloid suppressor cells in mixed lymphocyte assays, interleukin-6 (IL-6) secretion by myeloid leukaemia cells, and/or defects in T cell populations in myeloid leukaemia patients." (PMID 30678059, 2019). "The interleukin-6 (IL-6) family cytokine LIF was originally discovered as an inducer of differentiation and inhibitor of proliferation in a murine myeloid leukemia cell line, where it originally received its name." (PMID 34395259, 2021). "Another group has also suggested that miR-21 as a key oncomiR in MM.Our results show that BB down-regulates miR-21 levels in MM cell lines (RPMI-8266 and U226), but does not affect miR-21 levels in IL6-independent human myeloid leukemia cells (HL60, NB4, and K562 cell lines; data not shown)." (PMID 25000828, 2014).
Opportunistic infection (14 papers, 2009 to 2025). An infection that is caused by a pathogen that would generally not be able to cause an infection in a host with a normal immune system. "Patients with pancytopenia are at risk of severe opportunistic infections, therefore, they should have monitored inflammatory parameters such as C-reactive protein (CRP), procalcitonin (PCT) and interleukin 6 (IL-6)." (PMID 38882583, 2024). "Markers of inflammation that remain elevated include interleukin-6 (IL-6), C-reactive protein (CRP), and D-dimer, and have been associated with all-cause mortality and opportunistic infections." (PMID 38455337, 2022). "IL-6 is reportedly elevated during HIV infection and has been associated with mortality and opportunistic infections." (PMID 29027985, 2017). "It is important to note that opportunistic infections by intestinal Streptococcus can trigger an inflammatory response in the body, leading to the production of various inflammatory mediators within cells, such as IL-6, IL-8, and TNF-α." (PMID 38399774, 2024). "Elevated levels of inflammatory biomarkers including IL-6, IL-10, and tumor necrosis factor (TNF)-α were observed in patients with opportunistic infections in the 2DR arm at baseline." (PMID 34983415, 2022). "Second, the absence of detailed data on opportunistic infections and other co-infections, which could potentially influence IL-6 levels and contribute to the complexity of the immune response observed in INR patients, limits our ability to draw comprehensive conclusions." (PMID 40310370, 2025).
Oral ulcer (14 papers, 2020 to 2026). Erosion of the mucous mebrane of the mouth with local excavation of the surface, resulting from the sloughing of inflammatory necrotic tissue. "PLHIV may be at high risk for COVID-19 pandemic induced-stress oral ulcers due to the elevated C-reactive protein, ferritin, and interleukin-6 that are also associated with oral ulcers." (PMID 37635219, 2023). "We found statistically significant positive associations with SLE disease activity index (SLEDAI) and damage index (SDI), physician and patient global assessment, C-reactive protein, leukocyturia, complement C4, IL-6 and oral ulcers." (PMID 38474267, 2024). "In the current evaluation, by contrast, increased levels of urinary IL-6 were preceded by decreases in urinary protein and increases in oral ulcers and were followed by increases in urinary protein and decreases in oral ulcers." (PMID 34975831, 2021). "Additionally, IL-6 mRNA was upregulated in the oral ulcer region, suggesting increased Hamp and hepcidin levels via the IL-6/STAT3 pathway owing to inflammation in the OUM model." (PMID 37079608, 2023). "The levels of inflammatory cytokines IL-6, TNF-α, IL-18, and IL-1β in the oral ulcer group were significantly higher than in the normal group." (PMID 40818135, 2025). "In oral ulcers, the application of acetic acid elevated proinflammatory cytokines such as TNF-α, NF-κB, and IL-6 buccal contents by 246%, 345%, and 558%, respectively, compared with the normal control group." (PMID 40809172, 2025). "The topical application of chrysin significantly reduced the levels of IL-6 and TNF-α in acetic acid-induced oral ulcers." (PMID 40809172, 2025). "DEX not only reduces the production of inflammatory cytokines, such as IL-6, TNF-α, and NO, by LPS-induced inflammation but also reduces MDA levels in rabbits suffering from oral ulcers." (PMID 36474235, 2022). "After normalizing saliva for protein content, BD patients with oral ulcers (BD-MA) had significantly higher levels of salivary IL-1β (p=0.01), IL-8 (p=0.02), TNF-α (p=0.004) and IL-6 (p=0.01) than HCs." (PMID 35003055, 2021). "Therefore, chrysin’s ability to reduce NF-κB activation and subsequently lower cytokine levels, such as IL-6 and TNF-α, is a crucial aspect of its therapeutic potential in managing oral ulcers and other inflammatory conditions." (PMID 40809172, 2025).
Pancytopenia (14 papers, 2009 to 2026). An abnormal reduction in numbers of all blood cell types (red blood cells, white blood cells, and platelets). "Severe CRS has been demonstrated to be associated with infections which may be related to liver secreting acute inflammatory proteins induced by IL-6 and pancytopenia caused by severe CRS." (PMID 35799791, 2022). "CpG-injected WT mice receiving double treatment, show improvement in pancytopenia, hepatosplenomegaly, and liver inflammation, with reduced expression of inflammatory cytokines (Il6, Il12b, and Tnfa) compared with untreated mice." (PMID 41561071, 2026). "Persistent fever, severe pancytopenia, increased IL-6 (189.5 pg/ml) and fibrinogen (6.4 g/l), and extremely high ferritin levels (23,960 ng/ml) developed." (PMID 37414968, 2024). "Abnormal laboratory findings include pancytopenia, elevated liver function tests, raised C-reactive protein and interleukin-6 (IL-6), and hypergammaglobulinemia." (PMID 21615962, 2011). "In future, cytokine measurements such as IL-6 and IL-10 may become one of the factors elucidating the mechanisms of immune reaction that results in pancytopenia." (PMID 27885344, 2016). "Here, we demonstrate that lymph node (LN) cells from B6-based donor mice carrying IL-6, TLR2, or TLR4 gene deletions were fully functional in inducing severe pancytopenia and bone marrow failure (BMF) when infused into MHC-mismatched CByB6F1 recipients." (PMID 33711076, 2021). "Pancytopenia and significantly serum cytokines level rise were observed, including IFN‐γ, IL‐6, and IL‐10." (PMID 31050207, 2019). "Abnormal laboratory findings include pancytopenia, abnormal function of liver and kidney, raised CRP, IL-6 and hypergammaglobulinemia." (PMID 19400935, 2009). "Studies have shown that T cells lacking IL-6 led to pancytopenia and BMF as well as deletions on the IL-6 gene were inducing a variable degree of immune-mediated BMF, however, these studies do not indicate a significant or a direct role of IL-6 in murine BMF." (PMID 36032161, 2022). "We demonstrate that T cells lacking TLR2, TLR4, or IL-6 successfully induced severe pancytopenia and BMF." (PMID 33711076, 2021).